IL15 (interleukin 15)
Diseases named in the same sentence as IL15 in open-access papers (continued):
Sharing a sentence is not in itself a finding about the gene and the disease.
tumor (continued). "In mice, IL‐15‐rich environments cause an expansion of tissue‐resident ILC1‐like cells, which can limit tumour growth independent of NK cells." (PMID 32745353, 2020). "We sought to determine if increased local IL-15 expression, with or without the presence of IL-15Rα would result in greater anti-tumor response and protection." (PMID 33096755, 2020). "Contradictory to its role in promoting tumor progression of CRC, multiple studies suggest that IL-15 could execute its antitumor function through enhancing NK and CD8+ T cell cytotoxicity." (PMID 33419310, 2020). "We sought to investigate whether the combined treatment of IL‐15 and a CD40 agonist antibody may lead to augmented anti‐tumor responses in PDAC." (PMID 32821382, 2020). "Furthermore, immune cells activated by IL-15 have been shown to have a high capacity for cytokine secretion, including IFN-γ, TNF-α, TNF-β, GM-CSF, and IL-10, resulting in apoptosis of tumor cells." (PMID 33133514, 2020). "Testing combinations of various cytokines in T cell culture media revealed that tumor antigen specific CD4+ T cell growth was improved by culturing in IL-1β, IL-2, IL-6, IL-7, IL-15, IL-21, IL-23, and TGFβ, and that the addition of TGFβ was critical for the improved performance of the cocktail." (PMID 33362774, 2020). "Unfortunately, no complete tumor regression was achieved in mice treated with IL-15, IL-15cx with or without the depletion of MDSCs." (PMID 33628206, 2020). "Although CD4+ T cells increased approximately 30% in both IL-15 and IL-15cx treated mice compared to control tumor mice, the difference was not statistically significant." (PMID 33628206, 2020). "We generated CAR-T cells specific for human vascular endothelial growth factor receptor 1 (VEGFR-1) and T cells that genetically expressed IL-15, and the VEGFR-1-specific CAR-T cells delayed tumor growth and formation and suppressed pulmonary metastasis in a xenograft tumor model." (PMID 31637014, 2019). "Also, the activation of Tumor Necrosis Factor (TNF) family ligands that expressed on the surface of NK cells with IL-2, IL-15, IL-12, IL-18, and CD40 cytokines production induce NK cell cytotoxicity against tumor target cells and IFNγ production." (PMID 31457012, 2019). "IL-12/15/18- but not IL-15-activated NK cells were markedly effective in restraining tumor growth as determined by analysis of tumor burden 7 days after adoptive cell transfer, this correlating with their higher BM persistence and proliferation rate." (PMID 31699153, 2019). "It is tempting to speculate that a secondary effect of pharmacological STAT3 inhibition in cancer therapy may consist in a reduction of IL-15 dependent HIF-1α enrichment in NK cells, which may be expected to improve NK cell anti-tumor activity." (PMID 31681292, 2019). "Intriguingly, in mice treated with IL13-Rα2.IL-15-CAR T cells, tumors recurred at late time points and the majority of relapsed tumors no longer expressed IL-13Rα2, implicating antigen loss as a tumor escape mechanism in this model." (PMID 30828333, 2019). "In a study using the MC38 model, intraperitoneal IL-15 alone led to prolonged survival, but did not induce complete tumor regression." (PMID 31623390, 2019). "Furthermore, when tumour-bearing DCs were co-cultured with cryo-thermal eosinophils, the expression level of pro-inflammatory cytokines (CXCL10, IL-1β, IL-15 and IL-6) was increased as compared to tumour-bearing DCs co-cultured with tumour-bearing eosinophils." (PMID 31519961, 2019). "Furthermore, IL-15, a pro-cytotoxic cytokine, was reduced, whereas IL-6, an inhibitor of the STAT-5 pathway and of the NK cell function, was increased in the tumor." (PMID 31105699, 2019). "Select cytokines, like IL2, IL15, and IL12 perform stimulatory functions for T cells; in theory, autocrine secretion of these cytokines should help keep these cells persisting in vivo, even in the face of a hostile tumor environment." (PMID 31024832, 2019).
tumor (continued). "Interleukin-15 (IL-15) exhibits biological activities similar to those of interleukin-2 and enhances the proliferation of CD8+ cytotoxic T cells and natural killer cells, which in turn eliminate tumor cells." (PMID 30150638, 2018). "Although, vaccination with the bicistronic TH/IL-15-based DNA vaccine resulted in enhanced tumor remission, we did not detect significantly increased levels of tumor-infiltrating CD8+ T cell." (PMID 30452438, 2018). "So, IL-2 or IL-15 increased the cytotoxic activity of NK cells but did not to increase the sensitivity of tumor cells to Avelumab-mediated ADCC." (PMID 30294328, 2018). "IL-12/IL-15/IL-18 has previously been reported to promote the activation of NK cells in the absence of tumor stimulation." (PMID 30400618, 2018). "Elevated IFN-γ expression induced by IL-12 and IL-15-primed NK cells in response to ADO did not translate to a proportionally-enhanced lytic activity against CD73+ tumor targets." (PMID 30425720, 2018). "Initial assessment of this fusion antibody showed enhanced tolerability relative to a non-targeted IL-15 fusion antibody and potent anti-tumor activity." (PMID 30400822, 2018). "When compared to the PBS treatment, 2 μg IL-15 showed no tumor inhibition, while P22339 at 5 μg and 15 μg doses exhibited 30% and 46% antitumor activity respectively on day 4 after treatment." (PMID 29769573, 2018). "Considering the important role of IGF-1 in tumor progression, we examined whether IGF-1 was responsible for the tumor growth advantage with IL-15 stimulation." (PMID 29255466, 2017). "To examine the effect of IL-15 on the proliferation of CD215+ myeloid cells, we performed flow cytometric analysis of both mouse tumor and splenic cells from tumor-bearing mice 4–8 weeks after tumor implantation." (PMID 29255466, 2017). "Our study further revealed that CD215+ myeloid cells, but not CD215− cells, respond to IL-15 and promote tumor growth." (PMID 29255466, 2017). "In addition, co-administration of IL-21 and IL-15 enhanced the expression of IFN-γ by CD8+ T cells and induced melanoma tumor regression." (PMID 28927416, 2017). "In this study, however, relatively low dose IL-2 (100 IU/ml) was used, some of the experiments used pure Vγ2Vδ2 T cells omitting accessory cells or used both IL-2 and IL-15, and the cells were not tested for their in vivo tumor activity." (PMID 28239463, 2017). "Functionally, we show that IL-15-transpresenting DC are equal if not better inducers of T-cell proliferation and are superior in tumor antigen-specific T-cell activation compared with DC without IL-15 conditioning." (PMID 28785596, 2017). "Finally, it has been suggested that both IL-15 and IL-21 are able to enhance the in vivo anti-tumor effects of CD8+ T cells and, in some cases, potentiate tumor regression." (PMID 28146052, 2017). "The adoptive transfer of murine splenic NK cells pretreated with IL-12, IL-15, and IL-18, but not naïve or IL-15- or IL-2-pretreated NK cells, into tumor-bearing mice effectively reduced tumor growth, than that of when combined with radiation therapy." (PMID 28955346, 2017). "The cultured tumor cells grew faster after stimulating the splenic cells with IL-15, whereas no growth advantage was observed when IL-15 or CD215 was blocked with specific neutralizing antibodies." (PMID 29255466, 2017). "In bortezomib-treated 4T1HA tumor-bearing mice, CD4+T-cells showed increased IL-2 production, CD11c+ dendritic cells showed increased IL-12 and IL-15 production, and HA-specific activated CD8+T-cells showed enhanced expression of IFNγ, granzyme-B and transcription factor eomesodermin." (PMID 28052005, 2017). "The addition of the IL-15 superagonist fusion protein complex ALT-803 enhanced the ADCC capacity of both anti-PD-L1 and M7824, and to levels that both agents now demonstrated similar levels of ADCC of tumor cells." (PMID 29088859, 2017).
tumor (continued). "This is seen with increased IL-12 and IL-15 production in tumor-bearing mice as compared to control mice with no tumor." (PMID 28052005, 2017). "In univariate analysis, tumor size (p < 0.001), tumor thrombus (p < 0.001), TMN stage (p = 0.004), UCSF criteria (p = 0.002), and recipient IL-15 rs10519613 genotypes (CA/AA versus CC, p = 0.001) were significantly associated with an increased risk of HCC recurrence." (PMID 29162948, 2017). "Furthermore, we found that human IL-15 mediated insulin-like growth factor-1 production in CD215+ myeloid cells and blocking IGF-1 reduced the tumor-promoting effect of IL-15." (PMID 29255466, 2017). "In xenograft tumor models, CD215+ myeloid cells, but not CD215− cells, responded to human IL-15 stimulation and promoted tumor growth." (PMID 29255466, 2017). "Tumor thrombus (OR = 3.591, 95% CI: 1.438–8.971, p = 0.006), UCSF criteria (OR = 3.922, 95% CI: 1.515–10.152, p = 0.005), and recipient IL-15 rs10519613 genotypes (CA/AA versus CC; OR = 5.143, 95% CI: 1.636–16.168, p = 0.005) were independent predictive factors of HCC recurrence." (PMID 29162948, 2017). "CD44 expression in IL-15/trastuzumab treated HTM was increased in spleen, tumor, and liver." (PMID 27835865, 2017). "Although Vγ2Vδ2 T cells grown in IL-15 did not mediate better anti-tumor immunity, synergistic effects between IL-15 and a second γC cytokine, IL-21, have been reported." (PMID 28239463, 2017). "The combinatorial treatment of the tumor-reactive CD8 T cells with rapamycin and of the recipient with IL-15 may provide a novel protocol for potentiating adoptive T cell immunotherapy." (PMID 26824989, 2016). "While BRAF-i had no substantial effect, MEK-i sharply reduced tumor cell lysis mediated by IL-2- and IL-15-activated NK cells." (PMID 27563819, 2016). "In addition, the exposure to IL-15 also promotes an optimal response of CD8+ Tm cells with rapid division following antigen re-counter, and enhanced protective capacity against tumor cells." (PMID 27158441, 2016). "Recently, two functionally distinct subsets of splenic NK cells, namely DNAM-1+ and DNAM-1− NK cells, were described: Highly proliferative DNAM-1+ NK cells show an enforced IL-15 signalling and can give rise to DNAM-1− NK cells with reduced anti-tumour activity." (PMID 27982126, 2016). "In addition recombinant IL15 has also been shown to be presented by B-CLL tumor cells to NK cells in vitro where it leads to NK activation and subsequent tumor cell lysis." (PMID 27655680, 2016). "In the AOM/DSS model of CAC, Il15−/− but not Il15ra−/− mice showed higher tumor incidence and tumor size than WT counterparts." (PMID 27148488, 2016). "When IL-15 is infused in the brain of NK cell-depleted mice, no significant reduction in tumour volume is observed, demonstrating that NK cells are necessary for the antitumour activity of IL-15." (PMID 25818172, 2015). "We do know that a low percentage of these cells can be found in IL-15 TG mice in other organs such as the spleen (data not shown), so they are not completely unique to the tumor environment." (PMID 25879689, 2015). "While IL-15 has been under investigation as a cancer immunotherapeutic for the last decade, investigation has focused on tumor models that do not closely mimic spontaneous tumor formation in humans." (PMID 25879689, 2015). "In the absence of IL-15 the preventive vaccine significantly delayed tumor onset but all mice developed tumors with a greater multiplicity." (PMID 25997501, 2015). "Other reports showed that IL-21 combined with IL-15 preserved memory type features and CD28 expression of human CD8+ tumor-infiltrating lymphocytes (TILs) or CTLs induced by antigen priming, allowing the generation of expanded CTL populations suitable for in vivo use." (PMID 25961061, 2015).
tumor (continued). "The evidence that cytokines and leukotrienes can increase each other's receptor expression suggests that IL-2, IL-15, and LTB4 may synergize to augment NK cell migration to tumour or infection sites and enhance cytotoxic responses." (PMID 26696753, 2015). "IFN-γ production following in vitro co-culture of splenocytes of vaccinated IL15KO/NeuT mice with tumor cells was comparable to that of vaccinated NeuT mice suggesting that the ability of splenocytes to produce IFN-γ was not affected by the lack of IL-15." (PMID 25997501, 2015). "These experiments also confirm that IL-15 is not required for naive CD4+ T cell homeostasis or tumor rejection in our system." (PMID 26405570, 2015). "Improving NK cell persistence in vivo via autocrine IL-2 and IL-15 stimulation, enhancing tumor targeting by silencing inhibitory NK cell receptors such as NKG2A, and redirecting tumor killing via chimeric antigen receptors, all represent approaches that hold promise in preclinical studies." (PMID 26113846, 2015). "In IL-15 TG/MT mice, NK1.1 positive (includes NK cells, NKT cells, NK1.1+ CD8 T cells) but not CD8 positive cells were the most important cells for increased survival and tumor destruction." (PMID 25879689, 2015). "Differently, IL-15 mRNA levels increase, on EE, in both brain hemispheres of tumour-bearing mice, not increasing in sham-operated mice." (PMID 25818172, 2015). "Since CD3 + CD8 + NK1.1+ cells were removed by the NK1.1 depletion, we cannot rule out a role for this cell type in the tumor destruction of IL-15 TG/MT mice." (PMID 25879689, 2015). "Thus, the present review aimed to provide an update on the potential application of IL-15 in the culture of CIK cells and tumor immunotherapy." (PMID 24748966, 2014). "In order to identify the roles of IL-2 and IL-15 during induction of tumor toxic function of CIK cells, we performed comparative transcriptome analysis between CIK cells prepared with IL-15 and IL-2 respectively by Ion PI mRNA sequencing (RNA-seq) for the first time." (PMID 25108500, 2014). "While IL-15 was clearly not required for tumor growth in this model, IL-15 was essential for anti-tumor immunity." (PMID 24416335, 2014). "Our results show that exposure of IL-15 DC to the HPV vaccine results in increased expression of phenotypic maturation markers, pro-inflammatory cytokine production and cytotoxic activity against HPV-positive tumour cells." (PMID 24979331, 2014). "Further analysis revealed a unique transcriptional profile in tumor cells that arise in the absence of IL-15 that included a significant increase in the expression of IL-1α and IL-1α-regulated cytokines." (PMID 24416335, 2014). "In vivo experiments in RAG1-/- mice showed that subcutaneous B16-F10 tumors treated with vMyx-IL15Rα-tdTr exhibited attenuated tumor growth and a significant survival benefit for the treated group compared to the PBS control and the control viruses (vMyx-IL15-tdTr and vMyx-tdTr)." (PMID 25329832, 2014). "So, after treatment with ttIL15 or wtIL15, the accumulated IL15 protein in the tumor environment is limited by the lack of available IL15rα." (PMID 24369443, 2013). "TIL were expanded from the tumor cell suspensions by stimulation with IL-2-, IL-15-, IL-21- or no cytokine-expressing aAPC, after which phenotype and function of the various cytokine-expanded TIL were analyzed." (PMID 23402380, 2013). "Interestingly, the IL-21 aAPC expanded CD8+ T cells demonstrated superior functional tumor recognition, with significantly higher IFNγ release levels than the CD8+ T cells expanded by IL-2 and IL-15 aAPC." (PMID 23402380, 2013). "Using tumor cells rather than IL-15 and IL-2 as stimulators also induced significant expression of CD86, but not CD80, on NK cells, both in vitro and in vivo." (PMID 24349559, 2013).
tumor (continued). "Mart-126L- and/or GP100154/209/280-specific CD8+ T cells could be detected to similar levels in fresh (i.e. unexpanded) and IL-2, IL-15 and IL-21 aAPC expanded TIL samples, indicating that tumor antigen specificity was maintained after aAPC-mediated expansion." (PMID 23402380, 2013). "In contrast, IL-2, IL-7 and IL-15 induced p-STAT5 in tumor-infiltrating T cells were not different from normal T cells." (PMID 23072591, 2012). "An important finding from this study is that IL-15 killer DCs do not induce cell death of tumor antigen-specific T cells, suggesting that their cytotoxic action is tumor-selective." (PMID 23284789, 2012). "Furthermore, in this study, we also show that IL-15 DCs, as would be expected from DCs, are capable of processing and presenting the WT1 tumor antigen to CD8+ T cells." (PMID 23284789, 2012). "IL-15 induces the proliferation of memory CD8+ T-cells independently of antigen and increases their effector function; accordingly, malignant pleural effusion T-cells treated with IL-15 exert cytolysis against autologous tumor cells." (PMID 23118782, 2012). "Human interleukin-15 (hIL15) has anti-tumor activities, but it is not convenient for tumor treatment because of its short half-life." (PMID 19422685, 2009). "The human CD56+ cells are able to produce IFN-γ in response to polyI:C and IL-15 and cells from reconstituted mice are able to respond to the human NK-sensitive K562 erythroleukemia cell line by producing IFN-γ and inhibiting tumor growth both in vitro and in vivo." (PMID 20027308, 2009). "That is, IL15 has been expressed before tumor transplantation in our pre-treated rAAV2-hIL15 study, but IL15 was not expressed before 3 weeks with tumor transplantation in our post-treated rAAV2-hIL15 study." (PMID 19422685, 2009). "Flow cytometry revealed that IFN‐γ is the predominant cytokine produced by NK cells upon IL‐12, IL‐15 and IL‐18 stimulation, and that AREG‐KO NK cell–CM induced more cell death than WT NK cell–CM, indicating that NK cell–derived AREG protects against IFN‐γ–mediated tumor cell apoptosis." (PMID 41082397, 2026). "NIR-PIT and IL-15 showed a synergistic effect regardless of preexisting tumor immunogenicity." (PMID 41410776, 2025). "Multiple tumor models (4T1, CT26, and B16F10‐OVA) demonstrated that biomimetic nanovaccine extended the cytokine's blood circulation with a half‐life 8.2‐fold longer than that of free IL‐15 and triggered broad‐spectrum antigen‐specific T cell responses while minimizing systemic adverse effects." (PMID 40600457, 2025). "We acknowledge that the experimental conditions involving different cytokines (IL-15 for NK cells and no cytokine for T cells) may have introduced variability such that IL-15 may contribute to some non-specific anti-tumor reactivity." (PMID 41550919, 2025). "Importantly, anti–glypican-3 CAR Vδ1 cells with secreted IL-15 co-expression augmented in vivo anti-tumor activity compared to those without secreted IL-15 co-expression." (PMID 40148988, 2025). "While IL-15 armoring has been incorporated in current clinical trials, emerging evidence suggests that alternative cytokine strategies may further enhance CAR-iNKT anti-tumor activity." (PMID 40718496, 2025). "Interestingly, IL-15 has been reported to suppress intestinal inflammation and even exhibit tumor-suppressive effects, regardless of the SFAs." (PMID 40431182, 2025). "However, constitutive systemic IL-15 can provoke excessive immune activation and severe CRS; engineering solutions that have shown promise include membrane-bound IL-15, inducible expression, or tethering to the CAR to limit exposure to the tumor locale." (PMID 41584600, 2025). "IL-15-armored CAR T-cells have been demonstrated to exhibit enhanced proliferation, improved anti-tumor efficacy, sustained killing upon repeated tumor challenges in vitro and in vivo, prolonged survival in tumor-bearing mice, and promotion of central memory or stem cell memory-like phenotypes." (PMID 41019052, 2025).